CD4 (CD4 molecule)
Diseases named in the same sentence as CD4 in open-access papers (continued):
Sharing a sentence is not in itself a finding about the gene and the disease.
tumor (continued). "The autologous tumour-killing activity of CTLs was suppressed by the elimination of CD4+ cells." (PMID 8932341, 1996). "Moreover, we succeeded in a specific targeting of the expanded CD4+ helper/killer T cells to c-erb B-2 positive tumour cells by means of anti-CD3 x anti-c-erb B-2 bispecific antibody." (PMID 1353365, 1992). "Via Tumor Immune Estimation Resource (TIMER), we next determined whether the EGFR mutation may influence the abundance of immune infiltrates (B cells, CD8+ T cells, CD4+ T cells, macrophages, neutrophils, and DCs)." (PMID 41144813, 2026). "In addition, FA-CS-R848/DOX@Lip increased the MHC II/CD206 ratio of tumor-associated macrophages (TAMs), elevated the proportions of CD8+ and CD4+ T cells, reduced the proportion of myeloid-derived suppressor cells (MDSCs), and enhanced the percentages of IFNγ+ and Ki67+ CD8+ T cells in vivo." (PMID 42220424, 2026). "Indeed these cells might be important for direct tumour killing, a proposition strongly supported by murine modelling demonstrating that cytotoxic, exhausted, Tfh-derived CD4+ cells are able to directly kill MHC-lI+ tumor cells." (PMID 41542042, 2026). "However, CD4 T cells are equally critical for effective anti-tumor responses." (PMID 40076932, 2025). "Moreover, compared to monotherapy of anti-CTLA-4 antibody, this combination treatment increased CD8+/CD4+ ratio in T cells and reduced the number of regulatory T cells and myeloid-derived suppressor cells within the tumor microenvironment, enhancing anti-tumor immunity." (PMID 40611940, 2025). "Additionally, enhancing the expression of MHC II on antigen-presenting cells (APCs) can enhance the helper function of CD4+ T cells, which is crucial for maintaining an effective anti-tumor immune response and improving the success rate of vaccines and immune checkpoint blockade therapies." (PMID 41159033, 2025). "Importantly, treatment with fruquintinib remodeled the tumor immune microenvironment of MC38 tumors by increasing the percentages of CD4+ and CD8+ T cells and selectively reducing myeloid cells, particularly CD11b+ populations of tumor-associated macrophages (TAMs) and type 2 dendritic cells." (PMID 41459512, 2025). "Therefore, the gene set identified in our analysis appears to perform better in predicting the response to ICI therapies targeting CD8+ T cells and inflammatory cytokine gene signature within the tumor tissue than those targeting CD4+ T cells and T regulatory cells." (PMID 41439026, 2025). "Additionally, TTN mutations may promote the infiltration of CD4 and CD8 T cells, altering the TIME and boosting anti‐tumour immune activation." (PMID 39748197, 2025). "This approach not only effectively primed CD8+ and CD4+ T cells within the body but also facilitated the ex vivo expansion of these reactive T lymphocytes, which were subsequently reintroduced into the patient’s system to efficiently target and eliminate tumor cells." (PMID 40563603, 2025). "Additionally, immune infiltration analysis revealed that these DEGs might remodel the tumor microenvironment by modulating memory CD4+ T cells and inducing a macrophage phenotype transition from M1 to M2." (PMID 40002911, 2025). "The observed decline in CD19+ B cells, CD4+ T cells, and the CD4+/CD8+ ratio, coupled with an increase in CD8+ T cells in high-risk (IPI 3-5) and advanced-stage (III/IV) patients, points to a state of progressive immune suppression within the DLBCL tumor microenvironment." (PMID 41244913, 2025). "Notably, immunisation of mice with irradiated squamous cell carcinoma has been shown to induce stem-cell memory-like neoantigen-tetramer positive CD4+ T cells, which provide durable protection against live tumour challenge and re-challenge, via CD40L-dependent help of endogenous CD8+ T cells." (PMID 40801654, 2025).
tumor (continued). "Our study found that increased infiltration of TILBs was associated with good prognosis, and TILBs might promote antitumor immunity in multiple ways, including presentation of tumor antigens to CD4+ T cells or enhancing antitumor immunity by producing tumor-specific antibodies." (PMID 40145017, 2025). "In the meantime, DC maturation caused by iNKT cells leads to conversion from tolerogenic to immunogenic adaptive immune responses, boosting downstream tumor-specific CD4+ or CD8+ T cell responses, and might potentially be exploited in adjuvant approaches for immunotherapy." (PMID 40297580, 2025). "However, the function of these CD4+ memory T cells in the tumour microenvironment may be impaired, limiting their anti‐tumour activity." (PMID 40696496, 2025). "Finally, we investigated whether AP-EVs-Th1 exert anti-tumor effects by stimulating tumor-specific CD4+ T cell proliferation and differentiation." (PMID 40504376, 2025). "Furthermore, KLRG1 may mark circulating cytotoxic CD4+ T cells with tumor-matched TCRs to allow their isolation, which we validate below." (PMID 40299576, 2025). "Finally, CD4 + FOXP3 + (T-regulatory) cells were the least abundant cell population in the tumor." (PMID 39751643, 2025). "In addition, activation of CD4+ T lymphocytes through immune checkpoint pathways has been shown to promote vessel normalisation, highlighting the synergistic effect between blood vessels and T-cell-mediated immunity in the tumour microenvironment." (PMID 40943273, 2025). "The decline in CD4+ T cell proportion following CRT may suggest impaired cell-mediated immunity, while the rise in CD8+ T cell proportion could be linked to the activation triggered by the release of tumor-associated antigens prompted by CRT." (PMID 40012553, 2025). "Additionally, resting memory CD4+ T cells play a key role in monitoring long-standing tumors or minimal residual disease, providing ongoing protection and aiding in the prevention of tumor reemergence." (PMID 39895793, 2025). "However, directly improving the function of CD8 or CD4 TILs to combat tumor growth may prove premature." (PMID 40724900, 2025). "Moreover, the ratio of CD4+ T cells and CD8+ T cells near proliferating tumor cells in BRCA1/2-deficient tumors is positively correlated with patient prognosis, suggesting that the coordination of immune surveillance through the spatial connection of cells improves the prognosis of patients." (PMID 40830526, 2025). "Taken together with the increased hexanoic acid concentration in tumor‐draining lymph nodes following hexanoate intake, these results strongly suggest that hexanoic acid exerts its effects during the priming phase of Th0 differentiation into other CD4+ T cell subtypes." (PMID 40847888, 2025). "Additionally, CD4 staining of tumor tissues revealed that the combined treatment significantly increased CD4 expression, suggesting that the BG combined with US activated the host immune response, leading to increased immune infiltration at the tumor site and enhancing its antitumor effect." (PMID 40013983, 2025). "However, their anti-tumor effects can be counteracted by CD4+ Tregs present within the tumor microenvironment, which may inhibit their cytotoxic function." (PMID 40361239, 2025). "These clusters included three CD4+ T-cell subsets, three CD8+ T-cell subsets, three CD45RA+ cell subsets, one B-cell subset, two Treg subsets, one macrophage subset, one tumor-associated neutrophil subset, one monocyte subset, and two unknown T-cell subsets." (PMID 41020815, 2025). "Furthermore, anti-tumor stem-like CD4 and CD8 T cells (also exhaustion precursors) can self-renew and give rise to terminally exhausted T cells as well as effectors, and TCF1hi stem-like T cells, but not terminally exhausted T cells, can be reinvigorated by checkpoint blockades to combat cancers." (PMID 40076932, 2025).
tumor (continued). "Additionally, spontaneous tumor neoantigen-specific CD4+ and CD8+ T-cell responses have been detected, which might have contributed to the outstanding outcome witnessed in this patient." (PMID 41067882, 2025). "Single-cell transcriptome analysis of tumor-infiltrating lymphocytes has revealed a heterogeneous population of CD4+ T cells with cytotoxic phenotypes varying across disease contexts, suggesting that the induction of CD4 CTLs depends on the immunological context and stimuli." (PMID 40070836, 2025). "Similarly, TCF1+ CD4+ T cells were enriched at the tumour border compared with total CD4+ T cells." (PMID 40745918, 2025). "This may explain why CD4+ T28zT2 T cells did not cause severe toxicity in tumor-free mice and xenografts." (PMID 40107245, 2025). "Gut microbial depletion was able to rescue the anti-tumor immune machinery with downregulation of MDSCs and upregulation of antigen-presenting dendritic cells, tumor-infiltrating CD4+ T cells, and CD8+ T cells; however, the macrophage polarization could not be reversed." (PMID 40104059, 2025). "Importantly, high RASD1 RNA expression correlated with improved survival in KIRC, LGG, and PAAD and our finding suggests that this could potentially be due to increased infiltration of CD4+ T cells and myeloid dendritic cells in the tumor microenvironment." (PMID 40362656, 2025). "Finally, immunohistochemical staining was employed to assess the ratio of immune cells infiltrating the tumor in syngeneic tumor allografts, revealing a notable rise in the counts of CD4+ and CD8+ T cells in EVO-treated mice, which indicates that EVO enhances T cell infiltration in tumors." (PMID 41304979, 2025). "Notably, context matters: in human NSCLC, apCAFs have been observed adjacent to—and capable of activating—CD4+ T cells, suggesting that even within the “apCAF” label, function can range from tolerogenic (Treg-inducing) to immunostimulatory, depending on tumor type and microenvironment." (PMID 40940809, 2025). "Notably, the significant enrichment of galectins in antigen processing and presentation pathways, phagosome formation, and the negative regulation of CD4-positive T cell proliferation implicates galectins as central modulators of the tumour–immune microenvironment." (PMID 41516291, 2025). "Notably, CD4+ T cells, central memory CD8+ T cells and effector memory CD4+ T cells were significantly enriched in cluster 2, suggesting that cluster 2 may have a more robust and sustained anti‐tumour immune response within the PCa microenvironment." (PMID 40576161, 2025). "Indeed, alterations in KEAP1 and/or STK11, which are especially frequent in KRAS-mutated tumours, promote an immunosuppressive tumour microenvironment, enriched in suppressive myeloid cells and depleted in CD8+ cytotoxic T cells, but with relative sparing of CD4+ effector T cells." (PMID 40849356, 2025). "Analysis of the tumor microenvironment showed that the densities of intralesional CD8+/CD4+ T cells and M1 macrophages in males were 40%–60% lower than those in females, indicating that insufficient immune infiltration may contribute to a more aggressive tumor phenotype." (PMID 41333481, 2025). "This indicates that the UCK2 gene may exerts anti-tumor immunity effects through CD4+ T cells." (PMID 39931080, 2025). "Immunohistochemical analysis of pre-treatment tumor biopsies from 73 HNSCC patients receiving radical chemoradiotherapy revealed that mitochondrial-rich (COX5B) metabolism correlated with higher intra-tumoral CD8/CD4 ratios, whereas glucose-dependent (GLUT1) metabolism correlated with lower ratios." (PMID 40356601, 2025). "In addition, TAGAP, as a c-Rel suppressor in CD4+ T cells could promote their differentiation into Th1/Th17 cells and inhibit their differentiation into Tregs, thereby rejuvenating the anti-tumor ability of CD4+ T cells." (PMID 39998561, 2025).
tumor (continued). "Using the GSE162454 tumor samples, we performed dimensionality reduction and cell-type annotation, identifying eight major lineages—malignant cells, monocytes/macrophages (Mono/Macro), fibroblasts, osteoblasts, endothelial cells, CD4 Tconv lymphocytes, CD8 Tex cells, and plasma cells." (PMID 41488055, 2025). "In many tumor types, the expression of RAB5B is positively correlated with the infiltration level of neutrophils in B cells, Cancer-Associated Fibroblasts, Progenitor cells,endothelial cells, Dendritic Cell, CD4+ T cells,mast cells,Monocyte, Neutrophils and Treg." (PMID 40842984, 2025). "Firstly, while our trajectory and scTCR/BCR-seq sharing analyses support the intra-tumoral differentiation of CD8+ and CD4+ T cells as well as B cells in mTLS, the origin of the T and B cells, whether already in the site of tumor or from the organ, such as tdLNs or blood, is unclear." (PMID 40335494, 2025). "Interestingly, changes in the CD4+ Tconv subset within the tumor were far less discriminative than those in the tdLN, likely reflective of the known predominant role of CD8+ T cells in mediating antitumor immunity and corresponding immunotherapy resistance upon sucralose treatment." (PMID 40742298, 2025). "Classification of these cells using the scATOMIC tumour microenvironment cell type classifier, indicated that the T CCL5high population consists primarily of Effector/Memory T cells (77/103), while the other T cell cluster consists predominantly of Naïve CD4+ T cells (152/223)." (PMID 40438247, 2025). "Furthermore, animal studies indicate that lung antigen-presenting cancer-associated fibroblasts (apCAFs) can directly activate CD4+T cells via MHC II presentation and secrete C1q, This secretion inhibits CD4+T cell apoptosis and bolsters anti-tumor immune responses." (PMID 40433386, 2025). "Notably, blocking HLA-DR or depleting CD4+ T cells impaired CTLs activation, suggesting a critical role for antigen presentation by CTLs to CD4+ T cells through HLA-DR in promoting robust anti-tumor responses." (PMID 41050699, 2025). "However, how PD-1 inhibitor affects the phenotype of CD4+T cells in the immune microenvironment and how CD4+T cells enhance the response of tumor tissues to immune responses are still unclear, and further studies are needed to clarify the cellular biological mechanisms." (PMID 40176817, 2025). "CD4+ T-cell subsets can exert both anti-tumor and pro-tumor effects: Th1 cells enhance cytotoxic immunity and are generally associated with favorable outcomes, whereas Th17 cells and regulatory T-cells may promote inflammation-driven tumor progression or suppress effective anti-tumor responses." (PMID 41462871, 2025). "Importantly, the upregulation of Bcl-6 to T-bet at the late stage, coinciding with the time when the anti-viral response waned but anti-tumor responses persisted, allowed for the expansion of a memory CD4+ T-cell subset that was responsible for long-lasting protective anti-tumor immunity." (PMID 39885128, 2025). "When tested on BALB/c mice, the in vivo findings complemented in vitro studies in that LPPR could aid anti-PD-L1 to overcome its resistance by damaging CAFs and improving anti-tumor immunity, as indicated by increased cytotoxic T cell (i.e., CD3+, CD8+ and CD4+) infiltration to the tumor." (PMID 40430851, 2025). "In our study, the increase in CD4+ T cells observed after combined nCRT and PD-L1 inhibitor treatment may contribute to enhanced antitumor immunity via immune surveillance and modulation of the tumor microenvironment." (PMID 40936903, 2025). "However, compared to the FAST‐treated groups, the depletion of CD4+ T or CD8+ T cells partially diminished the anti‐tumor effect of FAST, suggesting that both CD4+ T and CD8+ T cells play critical roles in suppressing tumor progression in the FAST treatment group." (PMID 40135850, 2025).
tumor (continued). "Thus, to test whether the immunization with KLH-AM mRNA vaccine was able to modulate lymphocyte infiltration, we stained tumor sections with antibodies against CD4 and CD8." (PMID 41226782, 2025). "Interestingly, although both Ce6 liposomes and hybridexosomes could promote dendritic cell maturation, only light-irradiatedhybrid exosomes induced robust tumor antigen-specific CD4+ and CD8+ T-cells in vitro." (PMID 39862206, 2025). "CD4 CTLs are helper T cells that can exert direct cytotoxicity in the context of chronic viral infections or repeated antigen stimulation in the inflamed tissue or the tumor microenvironment in a major histocompatibility complex (MHC) class II-dependent manner." (PMID 40070836, 2025). "Thus, PD-1 expression in MDV-transformed CD4+ T-cells may reflect cellular characteristics before transformation and the factors in the tumor microenvironment." (PMID 40430752, 2025). "Cluster A was characterized by a higher overall infiltration of immune and T cells, with increased proportions of exhausted CD4+ and CD8+ T cell subsets and prominent infiltration of M2-like macrophages, which are typically associated with immunosuppressive tumor environments." (PMID 40643554, 2025). "Rosenberg's team transferred CD4+ T helper 1 cells, which could recognize a mutation in ERBB2IP expressed by tumor cells from a patient with metastatic cholangiocarcinoma, resulting in tumor regression." (PMID 40948427, 2025). "However, while the ratio of tumor-infiltrating immune cell types was slightly different between the two tumor cell lines, it was not significantly changed between groups and was composed mainly of CD4+ and CD8+ T cells." (PMID 41221280, 2025). "Tumor microenvironment (TME) analysis using CIBERSORT revealed that the high-risk scoring group had lower proportions of regulatory T cells (Tregs), monocytes, resting mast cells, memory B cells, resting dendritic cells, activated mast cells, and resting memory CD4+ T cells." (PMID 40124684, 2025). "To validate our hypothesis, we utilized a tumor cell‐CD4+ T cell coculture model." (PMID 40056047, 2025). "Notably, CD4+ T cells were increased in the EphA2-overexpressing tumor-bearing lungs." (PMID 40867322, 2025). "Consequently, the ratios of both total and activated CD8+ and CD4+ T cells relative to Treg cells in the tumor more strongly favored the effector cells following Y33 IC alone or ICIs plus Y33 IC treatment compared with untreated mice and mice treated with ICIs alone or ICIs plus Control IC." (PMID 40789741, 2025). "In addition, the higher proportions of CXCR5+ non-Treg cell populations among CD4+ T-cells from patients with CLL were significantly associated with a lower tumor distribution (TD) value, predominantly representing lymph node involvement." (PMID 40427031, 2025). "While generally cytotoxic, Tc1 cells produce cytokines such as interferon-γ (IFN-γ), tumor necrosis factor-α (TNF-α), and granzyme B, which may exert immunomodulatory effects and, under certain conditions, support tumor progression through mechanisms that resemble those of CD4+ helper T cells." (PMID 40723153, 2025). "However, it was the density of tumor-associated macrophages (TAMs), rather than CD4 T-cell density, that held prognostic significance." (PMID 41256864, 2025). "Furthermore, we demonstrated that the significant association between the high expression of CD40 and the T-cell costimulatory molecules CD28 or GITR was most pronounced within the context of an "immunologically hot" tumor microenvironment, defined here by high CD4/CD8 RNA expression." (PMID 41182434, 2025). "Thus, MHC class I-restricted CD8+ T cells can recognise peptides sampling the entire proteome of the target cell, whilst MHC class II-restricted CD4+ T cells primarily recognise peptides of proteins that are present in the microenvironment, including proteins released from dying tumour cells." (PMID 40801654, 2025).